RNU6-73P (RNA, U6 small nuclear 73, pseudogene)
Synonyms: RNU6-73
Gene: Small nuclear RNA gene on chromosome 13 (27,828,763 to 27,828,869, forward strand). Ensembl gene ENSG00000207330.
Homologues: Orthologues: chimpanzee U6 (98% identical), dog U6 (94% identical), dog U6 (92% identical), guinea pig U6 (88% identical), pig U6 (79% identical). Paralogues in human: RNU6-12P (94% identical), RNU6-13P (94% identical), RNU6-25P (94% identical), RNU6-32P (94% identical), RNU6-41P (94% identical), RNU6-1 (93% identical), RNU6-16P (93% identical), RNU6-17P (93% identical), RNU6-18P (93% identical), RNU6-2 (93% identical), RNU6-20P (93% identical), RNU6-29P (93% identical), and 1289 more.